IGF1 (insulin like growth factor 1)
Diseases named in the same sentence as IGF1 in open-access papers (continued):
Sharing a sentence is not in itself a finding about the gene and the disease.
tumor (continued). "Control was defined as when insulin-like growth factor-1 (IGF-1) levels were within the normal range for the patient's age at 6 months after therapy, associated with decreasing tumour volume." (PMID 22024364, 2011). "Klk1, Klk21, Klk24 and Klk27 have been linked to Igf1-regulated tumour survival through degradation of the Igf binding protein Igfbp3 in humans." (PMID 21961992, 2011). "If the association was due to an effect of preclinical tumours on IGF1 (reverse causality), then it would be expected to be weaker in those with a greater time interval between blood collection and diagnosis." (PMID 20472501, 2010). "The overexpression of IGF-1 is associated with hyperplasia and neoplasia at an early stage in several animal models." (PMID 23675206, 2010). "It is worthy to note that colon 38 adenocarcinoma growth was significantly inhibited in liver-specific IGF-1-deficient mice whereas injections with recombinant human IGF-1 displayed sufficiently promoted the tumour growth and metastasing." (PMID 21084729, 2010). "A simple text-mining search shows that HGF is eight-fold more strongly associated with tumor metastasis, whereas IGF1 is three times more strongly associated with drug resistance (χ2 = 564.15, df = 1, p < 0.01; Supplement S5)." (PMID 20011464, 2009). "The PTEN tumour suppressor encodes a phosphatase, and its daf-18 orthologue in Caenorhabditis elegans negatively regulates the insulin/IGF-1 DAF-2 receptor pathway that influences lifespan in worms and other species." (PMID 18836529, 2008). "In addition, IGF1 upregulates the expression of the anti-apoptotic proteins Bcl-2, Bcl-XL, and survivin, thus promoting a drug-resistant tumor cell phenotype associated with metastatic hMM." (PMID 40724880, 2025). "Chinese research suggests that tumor risk associated with rhGH treatment may be related to high IGF-1 and high GH levels." (PMID 40799818, 2025). "For instance, targeting hepatocyte growth factor (HGF)-MET or IGF-1/IGF-1R signaling pathways—both critical for maintaining DTP states mediated through tumor-associated fibroblasts (CAFs) and tumor-associated macrophages (TAMs)—has shown promise in preclinical models." (PMID 40894234, 2025). "In models of HFD-fed MC38 tumor-bearing mice, OVX_females had greater inflammation associated with macrophages in subcutaneous adipose tissue, elevated levels of insulin-like growth factor 1 (IGF-1), and a higher prevalence of M2-like TAMs compared to their female counterparts." (PMID 39030619, 2024). "Moreover, IGF1 is also linked to pro-tumor metabolic rearrangements, thus promoting CRC progression." (PMID 38891888, 2024). "Besides gliomagenesis, MADM has also been used to study the evolution of medulloblastoma and showed tumor cells transdifferentiate to astrocytes, which promote the cancer progression via increasing the release of IGF1 from the tumor-associated microglia." (PMID 37734556, 2023). "The association between serum IGF-1 or tumor IGF-1R activity and PCa has been reported." (PMID 36831629, 2023). "Igf1 signaling has also been implicated in tumor growth, metastasis, drug resistance in PDAC." (PMID 37954069, 2023). "Transcriptomic analyses of these tumours suggested that obesity was associated with tumour metastasis, invasion, inflammation and cell death resistance, which were mediated by oestrogen signalling, hyperinsulinemia, IGF-1 and adipokine secretion." (PMID 37173907, 2023). "Additionally, there are studies published that underline the contribution of GH and IGF-1 in the process of tumor formation by stimulating cell proliferation, leading to increased mitosis." (PMID 37374352, 2023). "Chronically elevated IGF-1, and/or increased IGF-1 bioavailability and sensitivity, receptor expression, and amount of Ras protein prenylation are strongly implicated in neoplasia and ageing, whilst IGF-1 knockdown within in vivo models show improved longevity." (PMID 37958602, 2023).
tumor (continued). "However, in contrast to LNCaP, IGF-1 did activate VCaP tumor cell growth and caused diminishment of the integrins α5, αV, and β1, pointing to differences between the LNCaP and VCaP cell lines." (PMID 35053528, 2022). "A previous study demonstrated that a high-carbohydrate diet could cause acid reflux and increase cell proliferation and tumor growth caused by elevating aerobic glycolysis or activating the insulin-like growth factor-1 (IGF-1) axis." (PMID 35684033, 2022). "High IGF-1R expression and elevated IGF-1 circulating levels have been correlated with the increased risk and progression of BC with poor prognosis through promoting cell proliferation, invasion, anti-apoptosis, and tumor angiogenesis." (PMID 35843988, 2022). "Hence, apart from CEA, CA19-9, and other commonly used biomarkers of CRC, serum level of IGF-1 and the ratio of IGF-1 to IGFBP3 are potential novel tumor makers with diagnostic and prognostic relevance in patients with coexisting CRC and T2DM." (PMID 35296101, 2022). "The TME of the SHH-MB subgroup was studied by mosaic analysis with double markers, and it was found to contain astrocytes active in secreting IL4, in turn stimulating IGF1 production by tumor-associated microglia, whose metabolic signalling was involved in MB progression." (PMID 36005596, 2022). "In addition, it was shown that miR186 targets ROCK-1 (Rho-associated protein kinase 1) and IGF1 (Insulin-like growth factor 1) in tumor cells." (PMID 35444657, 2022). "In addition, significantly reduced levels of the proliferative protein IGF-1, associated with tumour development, were observed." (PMID 36235868, 2022). "Tumor-associated macrophages are known to secrete IGF-1/IGF-2 in the tumor microenvironment." (PMID 35008602, 2021). "Arctigenin intervention significantly reduced tumor growth by 45%, associated with decreased circulating FFAs and adipokines/cytokines including IGF-1, VEGF, and MCP-1, along with decreased AR, Ki67, and microvessel density and increased Nkx3.1 expression in tumors." (PMID 31996731, 2020). "Furthermore, the genotypes of IGF‐1 gene rs2195239 polymorphism were related to the tumor size, tumor clinical stage, and pathological types for GC patients." (PMID 32147868, 2020). "Given the radioprotective effects of IGF-1 signaling in tumor cells, the reduced IGF-1 levels in elderly individuals could be linked to susceptibility to irradiation injury." (PMID 32708958, 2020). "IGF-1 deficiency can confer protection against tumor progression." (PMID 32370764, 2020). "In addition, IGF‐1 gene rs2195239 polymorphism correlated with the tumor size, tumor clinical stage, and pathological types for GC patients." (PMID 32147868, 2020). "IGF1 deficiency, on the other hand, might confer protection against impending development of a tumor." (PMID 31208077, 2019). "This is due to the notable reductions in GH and IGF-1 after tumor debulking, whether the tumor is totally or partially resected, and will cause decreased IR and elevated insulin sensitivity, thus gradually easing the IR-induced β-cell hyperfunction." (PMID 31736874, 2019). "It is possible that the anti-tumour activity of sFRP4 in vitro maybe associated with inhibition of the insulin/IGF-1 pathway through AMPK activation." (PMID 29385093, 2018). "The investigators suggested that the main tumour regressive effects of CRD might be associated with the decreased production of substances like IGF-1 and leptin." (PMID 30510663, 2018). "As to the source of IGF1, a recent study has revealed how, in the thymic microenvironment of murine T-ALL models and T-ALL primary patient samples, leukemic cells overexpressed IGF1R while tumor-associated dendritic cells (DCs) synthesized and released IGF1, which drove T-ALL growth ex-vivo." (PMID 29949919, 2018).
tumor (continued). "This energy stress acts as a press disturbance; the effects of which would be greater in the tumor cells than in the normal cells due to their dependency on fermentation energy metabolism, mitogens, anabolic signaling (IGF-1, mTOR, etc.), elevated redox stress, and mutational load." (PMID 28250801, 2017). "It is possible to reverse the effect of IGF1 by reducing the levels of insulin and insulin-binding protein, which may be the mechanism underlying its anti-tumor proliferative effects." (PMID 29241458, 2017). "Lastly, we will discuss clinical interventions that can be employed to counteract this IGF-1-deficiency and the tumor-promoting environment of geriatric skin, which may provide a way to reduce skin carcinogenic risk in older patients." (PMID 28245638, 2017). "Since IGF1 and X10 promote cell proliferation, this could lead to a manifestation of mutations and consequently modulation of tumor development and progression." (PMID 28173837, 2017). "The results we obtained may provide novel information on the mechanisms of host EphA4‐deficiency inhibiting tumor progression mainly via EphA4‐mediated IGF1 production." (PMID 26923183, 2016). "The relative risk (RR) [95% confidence interval (CI)] was calculated for tumor incidence, and the standardised mean difference (95% CI) was computed for levels of serum insulin-like growth factor-1 (IGF-1), leptin, and adiponectin using a random-effects meta-analysis." (PMID 27653140, 2016). "The addition of pegvisomant to somatostatin analogue therapy may allow further reductions in IGF-1 and may also reduce the risk of tumor volume increase." (PMID 26290466, 2016). "By contrast, most tumor cells harbor oncogenic mutations in the IGF-1 signaling pathway." (PMID 27282289, 2016). "In addition to the stimulating effects of IL-6 and IGF-1, loss of function mutations of the tumour suppression gene PTEN in several MM cell lines, results in phosphorylation of the mTOR substrates." (PMID 26097872, 2015). "This might suggest a tighter association between the IGF1 signaling pathway with clinical observations such as response to chemotherapy, distant metastasis, ER-alpha status, tumor subtypes and grades, as well as clinical outcomes such as patient prognosis." (PMID 26100469, 2015). "Angiogenic and growth/survival factors such as IGF-1 are induced in SS-TAMs, and our results are consistent with tumor cell apoptosis caused by hypoxia or growth/survival factor deprivation promoting angiogenesis or trophic factor production via TAM activation." (PMID 25702581, 2015). "More in-depth molecular analysis of the mouse tumors at the genome and proteome level is needed to further understand the underlying mechanism for the enhanced tumor formation by the IGF1 and X10 treatment conditions and their potential role in either enhanced tumor initation and/or progression." (PMID 25848982, 2015). "IGF-1 is a well-known growth factor associated with tumor growth." (PMID 25411122, 2014). "Accordingly, we propose that the association of low serum IGF-1 levels with poor prognosis in HCC may be attributable to mechanisms beyond development of tumor itself." (PMID 24586785, 2014). "As suggested earlier, given the capacity for tumor-associated stoma to secrete IGF-1 or IGF-2, paracrine loops may also affect the efficacy of IGF-1R targeted therapy." (PMID 24212944, 2011). "Therefore, the daily consumption of animal fats and red meat is correlated with increased cancer mortality, because these types of food induce the synthesis of IGF1 (insulin growth factor 1), an activator of the mTOR pathway which is associated with tumor progression." (PMID 37176098, 2023). "Other prior work has shown that tumor associated B cells may be associated with poor prognosis, confer resistance to targeted therapy via induced expression of IGF-1, and promote tumor progression via increased angiogenesis and support of lymph node metastasis." (PMID 31138334, 2019).
tumor (continued). "However, whether the tumor-associated myeloid cells participate in tumor progression through IGF-1 is still elusive." (PMID 29255466, 2017). "Notably, injection of IGF-1/IGFBP-3 complex improves weight loss in tumor-bearing mice." (PMID 26975989, 2016). "Igf1 exhibited low expression compared to Igf2 in the tumor cluster and very low expression in all other clusters, suggesting it had lower importance in this model." (PMID 41568176, 2026). "Combination therapy with PAS and PEG normalized IGF-1 and maintained radiological tumor stability during long-term follow-up." (PMID 42314763, 2026). "Growth hormone receptor (GHR) signalling enhances migratory ability of tumour cells and excess IGF-1 production promotes angiogenesis." (PMID 41700740, 2026). "Heat shock protein 70, insulin-like growth factor 1, and octamer-binding transcription factor 4 showed a higher expression in normal renal tissue with a progressive reduction across tumor grades." (PMID 42193301, 2026). "The addition of α-IGF1 nAb significantly diminished CAF-CM-mediated enhancement of tumor cell proliferation, colony formation and migration." (PMID 41275311, 2025). "IF enhances autophagy, lowers blood glucose and IGF-1 levels, and induces selective tumour cell death while preserving healthy cells, partly through modulation of the mammalian target of rapamycin (mTOR) and AMP-activated protein kinase (AMPK) pathways." (PMID 41335382, 2025). "Animal model studies have demonstrated that fasting triggers systemic changes, including reduced glucose availability and altered insulin and IGF-1 signaling, which can restrict the energy supply to tumor cells, thereby inhibiting their progression." (PMID 40296920, 2025). "Recent research highlights the distinct roles of IGF1 isoforms, including IGF1-Ea, IGF1-Eb, and IGF1-Ec, in promoting tumour growth, metastasis, and hormone signalling interactions, particularly with oestrogen." (PMID 39796756, 2025). "Elevated insulin drives tumor proliferation and metabolic reprogramming through IRs or enhanced IGF‐1 activity, particularly in breast, colorectal, and prostate cancers." (PMID 41267926, 2025). "First, we tested associations of endogenous IGF1 expression with CD274 (PD-L1 mRNA), finding significantly higher CD274 in tumours with the highest (n = 124) quartiles of IGF1 when compared with the lowest (n = 125)." (PMID 41184420, 2025). "Unsurprisingly, preclinical studies on breast, colon, and prostate cancer models have demonstrated that fasting protocols, by reducing IGF-1 signaling, effectively limit tumor growth as well." (PMID 39940361, 2025). "Several predictors of fgSRL resistance have been described previously and include male sex, younger age, initial GH and IGF-1 levels, high tumor volume, tumor hyperintensity on T2-weighted MRI and the expression of SSTR subtypes, among others." (PMID 40590355, 2025). "tumor cells are unable to synthesize arginine due to argininosuccinate synthetase 1 (ASS1) deficiency, and instead upregulate insulin-like growth factor 1 (IGF-1R) and enhance ASS1 transcription via c-MYC for arginine metabolic reprogramming." (PMID 39925801, 2025). "Utilising the multivariate Cox regression model, we developed a nomogram incorporating CTP, IGF-1 (low vs high) and tumour volume to predict patients' 1-year and 2-year survival probabilities." (PMID 39624154, 2025). "At the systemic level, metformin reduces hepatic gluconeogenesis and consequently lowers circulating insulin concentrations, thereby attenuating activation of insulin- and IGF-1-dependent signaling cascades that are frequently co-opted in tumor growth." (PMID 41157306, 2025). "Serum tumor marker concentrations were within normal reference ranges as were growth hormone (GH) and insulin-like growth factor-1 (IGF-1) levels." (PMID 40894918, 2025).
tumor (continued). "Nevertheless, some of the tumor-suppressing EV cargoes are Huh7-derived EV-miR-122, which, when received by HepG2 cells in vitro, leads to the overproduction of IGF-1 and has a tumor-suppressive effect." (PMID 40650114, 2025). "For instance, IGF‐1, vascular endothelial growth factor receptor (VEGFR), FGFR, and angiogenesis have been reported to be associated with tumor progression and the effect of immunotherapy." (PMID 40859961, 2025). "Previous work reported a positive correlation between IGF1 concentrations and tumor size in NPC patients, suggesting its potential as a diagnostic marker." (PMID 41333209, 2025). "This gene serves as a critical regulator across various signaling pathways closely linked to tumor progression and initiation, such as the P13K/Akt kinase, Ras/MAP kinase, and IGF-1-activated pathways." (PMID 40212965, 2025). "GH and IGF-1 can induce tumor development by promoting cell proliferation, and multiple PitNETs are relatively frequent (1.6–3.3%) in Cushing’s disease, suggesting the possibility of GH or ACTH related induction theory although supportive evidence is lacking." (PMID 40002269, 2025). "Previous study has shown that HBEGF promotes myocardial interstitial fibrosis via the Akt/mTOR pathway, suggesting a potential cooperative role with IGF‐1 in modulating QSOX2 expression in tumor cells through Akt/mTOR signaling." (PMID 40433832, 2025). "In our study, somatostatin receptor expression, ki-67, and postoperative values of GH and IGF-1, as well as the maximal postoperative tumor diameter, were the strongest predictors of outcome." (PMID 40276548, 2025). "Elevated levels of IGF-1 not only support tumor proliferation but also enhance the longevity and activity of osteoclasts, thereby worsening the extent of bone loss during disease progression." (PMID 40565082, 2025). "It has also been demonstrated that activation of the insulin/IGF-1 signaling pathway induces tumor cell growth and proliferation." (PMID 40427517, 2025). "FMD is intended to reduce glucose, insulin, and IGF-1 (which can promote tumour growth) levels but induce ketosis and fasting-like metabolic effects." (PMID 41335382, 2025). "These insights extend the role of IGF-1 beyond mere tumour characteristics, illustrating its broader implications for liver functionality and patient physiological status." (PMID 39624154, 2025). "We investigated IGF-1’s tumor-intrinsic immune effects in PCa to understand mechanisms underlying its poor immunotherapy response." (PMID 41184420, 2025). "Studies have shown that pasireotide can achieve better normalisation of GH and IGF-1 levels than comparative SRLs, as well as significant tumour volume reduction in many patients." (PMID 41287839, 2025). "Cabergoline dosage was increased to address elevated IGF-1 levels, but auditory hallucinations emerged as a side effect, leading to additional tumor resection under MRI guidance two years later." (PMID 40895665, 2025). "Residual or recurrent disease was defined by persistently elevated GH or IGF-1 levels and imaging-confirmed tumor presence after prior surgery." (PMID 40861590, 2025). "To further verify that CAF-derived IGF1 promotes tumor progression, we introduced anti-IGF1 neutralizing antibody (α-IGF1 nAb) into CM from CAF cells and performed functional assays." (PMID 41275311, 2025). "IGF1 + CAF were present in all tumour types and expressed all iCAF markers originally identified in PDAC." (PMID 39757146, 2025). "A multivariable Cox model including Child-Turcotte-Pugh (CTP) score, IGF-1, and tumor volume effectively predicted survival." (PMID 39624154, 2025). "IGF-1, in turn, strengthens homotypic tumor cell adhesion via E-cadherin and promotes the formation of multicellular tumor clusters, which enhances the efficiency of metastasis." (PMID 41516032, 2025).